RNU6-360P (RNA, U6 small nuclear 360, pseudogene)
Gene: Small nuclear RNA gene on chromosome 2 (208,019,638 to 208,019,741, reverse strand). Ensembl gene ENSG00000212246.
Homologues: Orthologues: chimpanzee U6 (100% identical), macaque U6 (90% identical), dog U6 (80% identical). Paralogues in human: RNU6-1094P (83% identical), RNU6-1035P (82% identical), RNU6-73P (82% identical), RNU6-761P (82% identical), RNU6-820P (82% identical), RNU6-97P (82% identical), RNU6-1216P (81% identical), RNU6-1249P (81% identical), RNU6-175P (81% identical), RNU6-536P (81% identical), RNU6-655P (81% identical), RNU6-668P (81% identical), and 1282 more.